RNF31 (ring finger protein 31)
Diseases named in the same sentence as RNF31 in open-access papers (continued):
Sharing a sentence is not in itself a finding about the gene and the disease.
metabolic syndrome (2 papers, 2017 to 2025). A cluster of metabolic risk factors for CARDIOVASCULAR DISEASES and TYPE 2 DIABETES MELLITUS. "Next, we investigated the correlation between the expression of RNF31 (HOIP) in visceral (V) adipose tissue from RNA-seq data of the Leipzig Obesity BioBank (LOBB) and various markers of the metabolic syndrome in serum of lean and mainly obese patients collected cross-sectionally." (PMID 40961178, 2025).
triple-negative breast carcinoma (2 papers, 2022 to 2026). An invasive breast carcinoma which is negative for expression of estrogen receptor (ER), progesterone receptor (PR), and human epidermal growth factor receptor 2 (HER2). "For instance, RNF31 mediates polyubiquitination of YAP at Lys76 in triple-negative breast cancer (TNBC) cells, thereby suppressing tumor growth, migration, and metastasis." (PMID 41522361, 2026). "Here, we demonstrate that RNF31 plays tumor suppressive function in triple negative breast cancer (TNBC)." (PMID 36581998, 2022). "Our studies further certified RNF31 could repress immune evasion via YAP/PD-L1 axis suppression in Triple Negative Breast Cancer." (PMID 36581998, 2022).
common variable immunodeficiency (1 paper, 2019). "Here we describe a second case of HOIP deficiency with compound heterozygous mutations in RNF31, who was clinically diagnosed with common variable immunodeficiency (CVID)." (PMID 30936877, 2019).
gastric cancer (1 paper, 2019). A primary or metastatic malignant neoplasm involving the stomach. "RNF31 expression has been correlated with intratumoral Treg cell activities in gastric cancer, indicating a potential role of RNF31 in tumor immunity." (PMID 31681337, 2019).
gastric tumors (1 paper, 2023). "In human gastric tumors, RNF31-mediated atypical ubiquitination stabilizes Forkhead box P3 and thereby stimulates regulatory T-cell function, thus promoting tumor progression." (PMID 37117215, 2023).
Hepatic steatosis (1 paper, 2025). Steatosis is a term used to denote lipid accumulation within hepatocytes. "Similarly, a study on the delivery of inherent RNF31 through EVs derived from mesenchymal stem cells revealed that RNF31 delivery significantly improved liver function by alleviating hepatic steatosis in high-fat diet-fed mice." (PMID 39773634, 2025).
lymph node metastasis (1 paper, 2021). "Univariate and multivariate Cox analyses revealed that RNF31 was an independent risk factor for prognosis, as well as lymph node metastasis, TNM stage, and distant metastasis." (PMID 33824292, 2021).
pancreatic cancer (1 paper, 2022). "Taken together, our results suggest that loss of the LUBAC subunit Rnf31 sensitizes murine and human pancreatic cancer to CTL killing by rendering cells susceptible to caspase-8-mediated apoptosis upon TNF signaling." (PMID 35379808, 2022). "Orthotopic transplantation of Vps4b- or Rnf31 deficient pancreatic tumors into immune competent mice, moreover, reveals increased CD8+ T cell infiltration and effector function, and markedly reduced tumor growth." (PMID 35379808, 2022). "Here, based on in vitro and in vivo CRISPR screens, the authors identify Rnf31 and Vps4b as drivers of immune escape, showing that loss of their function leads to an increase in T cell-mediated killing and reduced tumor growth in preclinical pancreatic cancer models." (PMID 35379808, 2022). "To next assess whether loss of Rnf31 also sensitizes human PDA to TNF-mediated cell death, we generated patient-derived and engineered human pancreatic cancer organoids (hPDA) with RNF31KO mutations and treated these organoids for four hours with TNF." (PMID 35379808, 2022).
sensorineural hearing loss (1 paper, 2023). "Regarding RNF31 variants involved in linear ubiquitination of NF-κB signaling components, regulatory variants in the NFKB1 gene have been reported to modify hearing outcomes in patients with MD and unilateral sensorineural hearing loss." (PMID 37273692, 2023).
thyroid carcinoma (1 paper, 2023). "In contrast, in kidney renal papillary cell carcinoma (KIRP) and thyroid carcinoma (THCA), RNF31 expression levels were lower than those in normal controls." (PMID 37117215, 2023).
tumor (31 papers, 2015 to 2026). "Pharmacologic blockade of RNF31 enhances bystander killing of MHC‐I‐deficient tumour cells, offering a potential therapeutic strategy for immune‐refractory cancers." (PMID 40673641, 2025). "Meanwhile, in TNBC, RNF31 was found to exert a tumour suppressive role via K48 linkage of the Yes‐associated protein (YAP) for degradation, which reduces Hippo signalling target gene expression." (PMID 39915011, 2025). "Inhibition or depletion of RNF31 rendered tumor cells more susceptible to both adaptive and innate immune cells, resulting in heightened apoptosis through reduced NF-κB signaling." (PMID 37876793, 2023). "Using an orthotopic transplantation model, we further demonstrate that loss of Rnf31 and Vps4b gene function leads to reduced tumor growth and increasing T cell infiltration and effector function in vivo." (PMID 35379808, 2022). "Our univariate analysis indicated that high RNF31 expression was a prognostic factor associated with poor survival (hazard ratio [HR], 2.31; 95% confidence interval [CI] 1.07–5.00; P = 0.034), as well as tumor classification and tumor growth patterns (P = 0.001 and P = 0.002, respectively)." (PMID 38172174, 2024). "Our data from TRAF2 KO combined with Birinipant treatment indicated a significant depletion of RNF31 in the TNFR1 complex in sensitized tumor cells, despite unchanged cellular RNF31 protein levels." (PMID 41315176, 2025). "Previous studies suggested that elevated RNF31 expression accelerates tumour progression and treatment resistance." (PMID 39915011, 2025). "Treatment with the RNF31 inhibitor Thiolutin overcame paclitaxel resistance and markedly impeded tumour progression in TNBC." (PMID 39915011, 2025). "CRISPR‐Cas9 screens under NK and CD8+ T cell pressure identified the LUBAC complex—particularly RNF31—as a key regulator of tumour resistance." (PMID 40673641, 2025). "The tumours in the IPO13 knockdown plus paclitaxel group were slightly smaller than those in the RNF31 knockdown plus paclitaxel group, while the difference was not statistically significant (p = .676)." (PMID 39915011, 2025). "The remaining tumours also showed strongly reduced nuclear ALYREF levels in tumour tissues of the RNF31 knockdown and IPO13 knockdown groups, as detected by western blotting and IHC assays." (PMID 39915011, 2025). "Consistently, the mRNA and protein levels of TUBB3, STMN1, and TAU were dramatically reduced in the tumour tissues of the RNF31 knockdown and IPO13 knockdown groups treated with PTX." (PMID 39915011, 2025). "It has been reported that RNF31 plays a multifaceted role in tumour proliferation, cell death, and the development of chemotherapy resistance in several malignancies." (PMID 39915011, 2025). "Our clinical and in vitro data showed that RNF31 is a prognostic factor for HCC that promotes tumor aggressiveness via NF-κB activation." (PMID 38172174, 2024). "In conclusion, our study demonstrated that RNF31 expression is an important prognostic factor for HCC, and RNF31 is involved in HCC tumor progression via the NF-κB pathway." (PMID 38172174, 2024). "The Tumor Immune Estimation Resource (TIMER) database was used to analyse the correlation between RNF31 and tumor immune cell infiltration in LIHC." (PMID 37117215, 2023). "Analysis of two of the strongest hits, Vps4b, and Rnf31, demonstrated that their inhibition sensitizes tumor cell clearance directly, via cell-autonomous mechanisms, and indirectly, by increasing the number and functionality of intratumoral CD8+ T cells." (PMID 35379808, 2022). "As the tumor stroma is known to be an important determinant for PDA prognosis and treatment, addressing the effect of Rnf31 and Vps4b depletion in the context of the tumor stroma would be highly valuable." (PMID 35379808, 2022). "For Rnf31 we demonstrate that it protects tumor cells from TNF-mediated caspase 8 cleavage and subsequent apoptosis induction, a mechanism that is conserved in human PDA organoids." (PMID 35379808, 2022).
tumor (continued). "The tumor lysis confirmed the RNF31 was overexpressed, while YAP expression was inhibited in TNBC tumors." (PMID 36581998, 2022). "To systematically explore which of these effector mechanisms are sensitized upon Rnf31 and Vps4b inhibition, we first assessed tumor cell sensitivity to TNF ligands." (PMID 35379808, 2022). "Our study revealed a tumor suppressive role of RNF31 to YAP protein ubiquitination and stability, which controlled the transcriptional regulation of Hippo target genes and TNBC progression." (PMID 36581998, 2022). "In the meanwhile, RNF31 depletion facilitated total CD45 immune cells as well as the infiltration of CD8+ T cells within the tumor mass." (PMID 36581998, 2022). "A chi-square test showed that RNF31 expression was associated with TNM stage and tumor size (P < 0.05)." (PMID 33824292, 2021). "Consistent with our results, the data provided by the Human Protein Atlas website showed that RNF31 was overexpressed in tumor tissues." (PMID 33824292, 2021). "Then, we performed RT-PCR and found that RNF31 expression in the tumor tissue was higher than that in the para-carcinoma tissue." (PMID 33824292, 2021). "Indeed, the off‐target effect of Thiolutin is also a promising target to inhibit tumours; however, further study is warranted to determine the anti‐cancer potential of RNF31 inhibition." (PMID 39915011, 2025). "RNF31 inhibition sensitizes tumours to NK and T cell‐mediated killing through TNF‐driven pathways." (PMID 40673641, 2025). "In ER‐positive breast cancer, RNF31 could activate estrogen signalling via monoubiquitination to facilitate tumour growth." (PMID 39915011, 2025). "Notably, the RNF31 inhibitor and paclitaxel synergistically repressed tumour growth in vivo and in TNBC patient‐derived organoids." (PMID 39915011, 2025). "Based on these results, we speculate that RNF31 may affect the composition of the tumor microenvironment." (PMID 37117215, 2023). "Ring finger protein 31 (RNF31) has been found to play an important role in tumor immunity." (PMID 37117215, 2023). "In summary, RNF31 was correlated with TNF and IFN-γ pathways, suggesting RNF31 may affect tumor immunity by participating in these cytokine-related pathways." (PMID 37117215, 2023). "RNF31 has been shown to play an important role in tumor immunity." (PMID 37117215, 2023). "The expression of RNF31 varied among different tumor molecular subtypes." (PMID 37117215, 2023). "While remaining Cas9 expression in these lines did not affect tumor growth, loss of Rnf31 and Vps4b markedly decreased tumor mass and resulted in significantly enhanced survival of tumor-bearing mice." (PMID 35379808, 2022). "Collectively, these findings suggest that RNF31 may act as a tumor suppressor in the normal liver parenchyma." (PMID 35869046, 2022). "We, therefore, speculated that the Rnf31 knock-out sensitizes tumor cells to TNF-mediated apoptosis either indirectly, by abrogating NFκB pro-survival signaling, or directly, by facilitating caspase 8 cleavage." (PMID 35379808, 2022). "The xenograft assay showed that RNF31 over-expression could inhibit TNBC tumor growth, while PD-L1 mAb treatment could further enhance tumor inhibition effect in RNF31 over-expression group." (PMID 36581998, 2022). "Moreover, Kaplan–Meier analysis demonstrated that RNF31 protein overexpression was negatively correlated with overall survival and tumor-free survival." (PMID 35869046, 2022). "The xenograft mice model indicated that RNF31 overexpression could inhibit TNBC tumor growing in MDAMB231 cells, while further YAP overexpression could at least partially rescue the growth inhibition caused by RNF31." (PMID 36581998, 2022). "In addition, we collected surgical samples to perform IHC assays and similarly found that RNF31 protein was overexpressed in tumor tissues." (PMID 33824292, 2021). "In addition, RNF31 expression can stabilize some membrane receptors of B cells and tumor cells, such as estrogen receptor α and CD4015–17." (PMID 33824292, 2021).
tumor (continued). "In this study we extend this observation by determining mRNA and protein expression levels of the two additional components of the LUBAC complex, RBCK1 and SHARPIN as well as RNF31 protein expression in the same cross sectional study of cancer tumors and adjacent non-tumor tissues." (PMID 29763465, 2018). "Notably, deficiency of RNF31 and IPO13 greatly impaired tumour progression upon PTX administration, as indicated by significantly reduced increases in the size and weight of the xenograft tumours." (PMID 39915011, 2025). "Therefore, we hypothesized that RNF31 may affect tumor immunity by participating in these cytokine-related pathways." (PMID 37117215, 2023). "Additionally, the expression of RNF31 varied in different tumor immune subtypes." (PMID 37117215, 2023). "Therefore, we speculated that RNF31 may affect tumor immunity by affecting the expression of autophagy-related molecules in LIHC." (PMID 37117215, 2023). "However, as T cell immunity is generally dependent on sufficient tumor antigenicity, future studies should determine whether Rnf31 and Vps4b depletion will show similar phenotypes in other PDA tumor models." (PMID 35379808, 2022). "Surprisingly, RNF31 depletion didn’t lead to TNBC cell inhibition, but showed even more aggressive phenotypes, which indicated it as a tumor suppressive player in TNBC." (PMID 36581998, 2022). "We identified Rnf31 and Vps4b in our in vitro and in vivo CRISPR screens using the OVA/OT-I tumor model, which ensured sufficient antigenicity of tumor cells." (PMID 35379808, 2022). "Besides, RNF31 could also prevent tumor immune evasion via inhibiting Hippo/YAP/PD-L1 axis." (PMID 36581998, 2022). "Depletion of several ubiquitinases and proteasome components (DTX3L, UBE2E1, RNF31, RNF115, USP2, USP42, PSMC3, and PSMD10) were also found to inhibit tumor cell migration." (PMID 31278301, 2019). "In contrast, our transcriptome data revealed that HOIP (Rnf31), HOIL-1 (Rbck1), and Sharpin, components of LUBAC, were more highly expressed in LSCC compared with LADC tumor cells, which was confirmed by quantitative PCR (qPCR) and immunoblotting." (PMID 30642944, 2019). "These correlations decreased for tumor tissues, as SHARPIN mRNA expression level was moderately correlated with RBCK1 and RNF31 mRNA expression levels (r = 0.52 and r = 0.48, respectively)." (PMID 29763465, 2018). "For TNBC with a high level of RNF31, Thiolutin plus PTX substantially reduced tumour growth." (PMID 39915011, 2025). "We found that RNF31 protein was highly expressed in most ERalpha-negative tumors relative to 10 ERalpha-positive tumor specimens (p = 0.034)." (PMID 29763465, 2018). "Since clinicopathological data for tumor samples including ERalpha, PR and HER2 protein expression and also clinical staging, histological grading, lymph node and menopausal statuses were available, we further examined the mRNA expression of RBCK1, RNF31 and SHARPIN in relation to these data." (PMID 29763465, 2018). "To understand the mechanism behind tumor sensitization, we compared the TNFR1 complex in WT and RNF31 KO tumor cells with and without HOPIN-8 drug treatment." (PMID 41315176, 2025). "ROC Curve analysis revealed that up-regulated RNF31, RBCK1 and SHARPIN mRNA expression had high predictive abilities to distinguish tumor tissues from adjacent non-tumor tissues, with the Area Under the Curves (AUCs) being equal to 0.95, 0.94 and 0.91, respectively." (PMID 29763465, 2018).
cancer (28 papers, 2010 to 2025). A tumor composed of atypical neoplastic, often pleomorphic cells that invade other tissues. "Our results suggested that RNF31 expression was positively associated with most of the major histocompatibility complex (MHC) molecules across human cancers except for ACC and KICH." (PMID 37117215, 2023). "There is compelling evidence from large-scale gene-drug association studies that RNF31 overexpression may contribute to cisplatin resistance in cancer." (PMID 35582023, 2021). "Splice-site mutations in the cancer-associated genes RNF31 and ATM also correlated with the skipping of exons harboring these mutations and may lead to a partial deletion of these proteins." (PMID 26109429, 2015). "RNF31 is a multifunctional RING finger protein implicated in various inflammatory diseases and cancers." (PMID 38172174, 2024). "We first analysed the expression of RNF31 in multiple human cancers and the relationship between RNF31 and immune cells using public databases." (PMID 37117215, 2023). "Taking the immune checkpoint gene LAG3 as an example, RNF31 expression was positively correlated with LAG3 in almost all cancers." (PMID 37117215, 2023). "We performed the Kruskal–Wallis test to analyse RNF31 expression in different immune subtypes across human cancers from TISIDB." (PMID 37117215, 2023). "Next, we explored the relationship between RNF31 expression and immune and molecular subtypes across human cancers." (PMID 37117215, 2023). "We also performed the Kruskal–Wallis test to analyse RNF31 expression in different molecular subtypes across human cancers from TISIDB." (PMID 37117215, 2023). "The Propidium Iodide (PI) coupled with Annexin V staining showed that RNF31 depletion inhibited cancer cell apoptosis in MDAMB231, BT549 and HS578T cells." (PMID 36581998, 2022). "Our study implicated a novel link with LUBAC complex with Hippo signaling in TNBC and a multi-faced function of RNF31 in cancer biology." (PMID 36581998, 2022). "As RNF31 was characterized as an E3 ubiquitin ligase in NFκB signaling transduction from these immunological and biochemical studies, more and more researchers started to focus on RNF31 function in cancer area." (PMID 27460922, 2016). "One is that RNF31 contributes its carcinogenic role by facilitating NFκB pathway, which is already shown to be the key oncogenic pathway in several cancers." (PMID 27460922, 2016). "In addition, a study found that enforced expression of RNF31 protected cancer cells from DNA‐damage‐induced apoptosis, leading to resistance to cisplatin." (PMID 39915011, 2025). "In addition, RNF31 was positively correlated with the levels of infiltrating immunosuppressive cells such as MDSCs and Tregs, both of which protect cancer cells from damage from the patient's immune system." (PMID 37117215, 2023). "We found that RNF31 expression was significantly higher in cancer samples than in normal samples." (PMID 37117215, 2023). "We believe a better understanding of RNF31 in LIHC may contribute to the further development of cancer immunotherapy." (PMID 37117215, 2023). "RNF31 has been found to be overexpressed and exhibit primarily oncogenic roles in several cancers." (PMID 37117215, 2023). "Previously published literature has also revealed key roles for RNF31 in cancers." (PMID 37117215, 2023). "The expression of RNF31 in cancer cells was higher than that in normal tissues." (PMID 37117215, 2023). "The findings of these studies are compatible with those of our study, revealing that the upregulation of RNF31 may act as a positively regulated effector of cancer." (PMID 35869046, 2022). "Due to the potentiated apoptotic response, RNF31 deletion may enhance the cytogenetic toxicity of cisplatin in some cancer cell lines." (PMID 35582023, 2021).